BRAF (B-Raf proto-oncogene, serine/threonine kinase)
Diseases named in the same sentence as BRAF in open-access papers (continued):
Sharing a sentence is not in itself a finding about the gene and the disease.
melanoma (continued). "Newer combinations of encorafenib and binimetinib potentially show even greater efficacy in BRAF-mutant melanomas." (PMID 32429485, 2020). "Treatment with the PAK inhibitor FRAX597 led to a decrease in Bad phosphorylation and induced more apoptosis within 24 h in BRAF mutant RhoJ positive melanoma cell lines than the BRAF inhibitors Vemurafenib and Trametinb." (PMID 32309283, 2020). "Tyrosine kinase inhibitors (TKI) targeting mutated BRAF and immune checkpoint inhibitors (ICI) have revolutionized advanced melanoma treatment and prognosis." (PMID 32585901, 2020). "Although BRAF mutations are more frequent in melanoma and papillary thyroid carcinoma in comparison with CRC, a few studies analyzed the effects of BRAF inhibitors (vemurafenib or dabrafenib and trametinib) in patients with metastatic CRC." (PMID 33374459, 2020). "Compared with patients with BRAF WT melanoma, those with BRAF(+) are often younger and present with superficial spreading tumors or tumors with nodular histology, developing in anatomical regions without chronic sun damage." (PMID 32605090, 2020). "The top 10 mutated genes in 467 melanoma patients are TTN (72%), MUC16 (67%), BRAF (51%), DNAH5 (49%), PCLO (44%), LRP1B (38%), ADGRV1 (35%), RP1 (33%), ANK3 (32%), DNAH7 (32%)." (PMID 33072607, 2020). "It has been shown to both overcome vemurafenib resistance in BRAF-mutant melanoma cells and prevent the rise of therapy-resistant melanoma persister cells." (PMID 32517051, 2020). "Similar findings have been observed in gefitinib-treated EGFR-mutant NSCLC and vemurafenib-treated BRAF-mutant melanoma." (PMID 33092283, 2020). "Statistics have shown that 30%–60% of melanoma, 30%–50% of thyroid cancer, and 5%–9% of CRC harbor BRAF mutations." (PMID 32665850, 2020). "The well-known BRAF and NRAS mutations in melanoma lead to the constitutive activation of the p44/p42 MAPK pathway, which upregulates iNOS expression." (PMID 32850409, 2020). "Taken together, these data indicate osteoblast‐derived RANKL alters the balance of death and proliferation that occurs when melanoma cells are treated with BRAF inhibitor to decrease apoptosis and increase cell‐cycle entry via upregulation of MITF." (PMID 31323160, 2020). "Consistently, the ectopic expression of RAC1P29S in melanoma cell lines increases resistance to BRAF and MEK inhibitor therapies." (PMID 33072757, 2020). "In this paper, we summarised the impact of miRNAs and lncRNAs on melanoma invasion and metastasis, pointing out their interference with BRAF inhibitors and immunotherapy." (PMID 33203119, 2020). "Low miR-579-3p expression in BRAF-mutated cells is linked to metastatic melanoma progression; expression levels of miR-579-3p decrease from nevi to stage III/IV melanoma samples and even further in cell lines resistant to BRAF/MEK inhibitors." (PMID 32054078, 2020). "It blocks proliferation of melanoma cell lines in BRAF and MEK inhibitor resistant cell lines in vitro." (PMID 32092958, 2020). "Here, using a preclinical mouse model, the authors show that during the early treatment phase with BRAF inhibitors, melanomas are highly immunogenic, with infiltrating T cells and natural killer cells." (PMID 31702822, 2020). "Mutant BRAF also downregulates the expression of melanoma differentiation antigens (MDA) and class I major histocompatibility complex (MHC-I) molecules on tumor cells, preventing their recognition by CD8+ T cells." (PMID 32731406, 2020). "In melanoma, BRAF and MEK inhibitors can induce an upregulation of the transcription factor PAX3, which in turn stimulates the expression of the microphthalmia-associated transcription factor (MITF), ultimately promoting cell survival." (PMID 33291749, 2020). "In a very interesting study, Hirata and collaborators demonstrated that BRAF inhibitors promote the formation of dense collagen fibrils and an overall increased matrix deposition by MAFs that render BRAF-mutant melanoma cells insensitive to treatment." (PMID 33212834, 2020).
melanoma (continued). "Only through thorough understanding of the mechanisms of BRAF inhibitor resistance can we hope to develop strategies for achieving the full therapeutic potential of contemporary treatments in patients with melanoma." (PMID 33003483, 2020). "Considering that higher BCL2 levels are associated with sensitivity to ABT-199 in other cancers, these data provide a rationale for testing the efficacy of BCL2 inhibitors, such as ABT-199 (venetoclax), in patients with BRAF-WT melanomas." (PMID 32764384, 2020). "BRAF and MEK inhibitors reduce metastatic burden for patients with melanomas harboring BRAF mutations; however, most eventually relapse due to acquired resistance." (PMID 33122628, 2020). "In melanoma, BRAF mutant ctDNA has been found to be a robust biomarker for disease burden and tumour status of patients prior to and during targeted treatment." (PMID 33339135, 2020). "Multiple effective systemic treatment options have emerged for patients with advanced BRAF-mutant melanoma over the last decade." (PMID 31817189, 2019). "In order to overcome this obstacle, we decided to incorporate the drug into targeted hyaluronic acid-based nanoparticles to target LM36R, a well-established human melanoma xenograft model of BRAF resistance." (PMID 30824801, 2019). "MEK1/2 inhibitors are clinically approved for the treatment of BRAF-mutant melanoma, where they are used in combination with BRAF inhibitors, and are undergoing evaluation in other malignancies." (PMID 35582726, 2019). "Recent pieces of evidence have shown that STAT3 activation is an important mechanism of resistance to targeted therapies against mutant BRAF, a critical oncogene in melanoma." (PMID 30622697, 2019). "We noticed a marked imbalance towards a higher overall survival of patients younger than 40 years old for both BRAF V600E positive tumor and the whole sample set, suggesting a different progression of melanoma for this group of patients." (PMID 31835364, 2019). "The identification of novel antimetastatic therapeutic targets is necessary for improved treatment of patients with acquired BRAF inhibitor‐resistant (BRAFi‐R) melanoma, in whom metastasis is a major concern." (PMID 30582770, 2019). "The lead compounds identified were then tested in predictive xenograft models of BRAF-mutant melanoma brain metastases." (PMID 30971321, 2019). "BRAF V600E increases the invasive potential of melanoma cells, but the down-stream effectors are not well known." (PMID 31039200, 2019). "This pathway plays a key role in inducing drug resistance after treatment of melanoma patients with BRAF/MEK inhibitors, and is thus a decisive target for melanoma therapy." (PMID 31470659, 2019). "BRAF-mutant melanoma can be treated with targeted therapy using mutant BRAF and MEK inhibitors in combination." (PMID 31623313, 2019). "Several targeted anti-melanoma agents, which are specific to one of the melanoma sub-types, have been proposed recently, including BRAF inhibitors, MEK inhibitors, c-Kit inhibitors, and so on9,10." (PMID 31273268, 2019). "This review will encompass in vitro and in vivo studies which investigated the modulation of the tumour microenvironment by BRAF-inhibitors, highlighting also the most recent clinical trials with a specific focus on melanoma and thyroid cancer." (PMID 31762942, 2019). "Mitogen-activated protein kinase (MAPK) pathway blockades are another class of molecules that can be used to effectively treat advanced melanoma; mainly composing of BRAF and MEK inhibitors." (PMID 30626368, 2019). "A 78-year-old female with advanced unresectable BRAF wild-type melanoma was treated with pembrolizumab (2 mg/kg 3-weekly)." (PMID 31488221, 2019).
melanoma (continued). "Available BRAF inhibitors utilized for the treatment of advanced BRAF-mutant melanoma include vemurafenib and dabrafenib." (PMID 31781977, 2019). "Multiregional analyses to include the precursor lesions have shown that BRAF and NRAS mutations are early drivers for melanoma tumorigenesis." (PMID 31277584, 2019). "In 2016, nivolumab in combination with ipilimumab was FDA approved for the treatment of patients with BRAF V600 wild-type and BRAF V600+ unresectable or advanced melanomas." (PMID 30975211, 2019). "This equivalence also contributes to the validation of these biomarker results, leading toward a better understanding of changes that occur within patients with BRAF- and NRAS-mutated melanoma and their predictive value." (PMID 30956763, 2019). "Magnolol, honokiol, and derivates were first assessed for their efficacy in NRAS‐mutant WM1366 and BRAF‐mutant WM164 melanoma cells by crystal violet assay." (PMID 30793515, 2019). "Accordingly, we evaluated the phenotypical and molecular changes of isogeneic human V600E BRAF-mutant melanoma cell line pairs pre- and post-treatment with vemurafenib." (PMID 31514305, 2019). "Proinflammatory cytokines have been demonstrated to facilitate melanoma cell proliferation and metastasis, as well as to contribute to BRAF inhibitor resistance." (PMID 31015455, 2019). "Non-ERK dependent mechanisms of resistance that do not rely on ERK signalling were described, as were other ERK independent pathways that sustain tumorigenicity of BRAF mutant tumours such as melanoma." (PMID 31126017, 2019). "BRAF and MEK inhibitors are currently used in advanced melanomas harbouring BRAF-activating mutations." (PMID 31450703, 2019). "BRAF inhibitors increase melanoma cell contractility, induce changes in cell shape by rewiring their cytoskeleton and activating the YAP/TAZ mechanotransduction pathway." (PMID 30254376, 2019). "In B-Raf proto-oncogene serine/threonine-protein kinase (BRAF) mutant (V600E) melanoma cells, a combination of BRAF inhibitor (BRAFi) with MEK inhibitor can induce protective autophagy." (PMID 31527477, 2019). "In particular, we showed the increased expression of BRAF in treated cells compared to untreated cells (NT), that is more evident in melanoma cells treated with (Bu3Sn)4TPPS." (PMID 31801187, 2019). "In the superficially spreading melanoma subgroup, BRAF V600E positivity indicated poorer RFS (p = 0.039) and OS (p = 0.012)." (PMID 31039200, 2019). "In parallel, Feng Zhang and colleagues reported the identification of genes whose overexpression in A375 melanoma cells gave rise to resistance against a BRAF inhibitor, an independent validation of the CRISPRa screening platform." (PMID 31921397, 2019). "Together, these studies suggest a modest response of intracranial disease to vemurafenib in BRAF-mutant melanoma." (PMID 31803366, 2019). "Of a particular significance, the finding that Ole was able to promote the death effect of Everolimus, a mTOR inhibitor, in Vemurafenib-resistant BRAF melanoma cells, points to a possibility for its use in treating resistant melanoma cells." (PMID 31766676, 2019). "Vemurafenib (PLX4032), a potent inhibitor of BRAF V600E that is recommended for cases of late-stage melanoma, prolonged patients’ overall survival from 9.9 to 13.2 months compared to standard chemotherapy." (PMID 31877948, 2019). "The association of AM404 and GSK126 induced a strong pro-apoptotic effect against three BRAFV600E-mutant melanoma cell lines previously characterized for intrinsic resistance to the BRAF-specific inhibitor PLX4720." (PMID 30710146, 2019). "Researchers with The Cancer Genome Atlas (TCGA) Network identified four genomic subgroups of melanoma: BRAF, NRAS, NF1, and triple wild-type." (PMID 30675668, 2019).
melanoma (continued). "In agreement with what has been observed in melanoma patients, we found that the dominating mutation in this cell line panel was BRAFV600E/K (34 of 49), whereas other mutations in BRAF, NRAS, or KRAS were less common (5/49, 8/49, and 1/49)." (PMID 31253656, 2019). "Compound 6a, merging the best inhibitory profile against the target kinases, showed anti-proliferative efficacy against the human melanoma cell lines A2058, expressing the BRAF V600D mutation, and WM266-4, expressing BRAF V600E." (PMID 31289333, 2019). "BRAF and NRAS mutations, while being well-known risk factors and drivers of cancer onset, have limited prognostic significance for overall survival of melanoma patients." (PMID 31316083, 2019). "Their therapeutic options are further limited because BRAF-wild-type melanomas frequently display treatment resistance due to activated MEK1 (MAP2K1), PKCα, PDGFR-β, AKT, or TNFα pathways." (PMID 31615091, 2019). "Vemurafenib was approved by the Food and Drug Administration (FDA) in 2011 as it blocks the serine/threonine kinase BRAF protein which is found in up to 50% of the melanomas." (PMID 31093406, 2019). "In some trials testing TARs, all cases had BRAF-mutant melanoma, whereas some other trials investigating IMMs enrolled both wild-type and mutant BRAF melanoma." (PMID 31762821, 2019). "Comparison of patients in the BRAF- and NRAS-mutated arms with TCGA melanoma cases showed overall concordance of the tumor genetic landscape with regard to the percentage of patients experiencing alterations in the most frequently mutated genes." (PMID 30956763, 2019). "Given that ∼40–50% of BRAFV600E/K melanoma patients fail to respond to BRAF inhibitors, there is room for improvement in the biomarker-driven selection of patients beyond simple genetic testing." (PMID 31253656, 2019). "Particularly, ERK-mediated S142 phosphorylation, rather than mTORC1-mediated S211 phosphorylation, is a predominant event in BRAF-mutant melanoma." (PMID 30979895, 2019). "Binimetinib showed an ORR of 20% and a median PFS of 4 months in BRAF-wt NRAS-mutant melanoma patients in a phase II trial." (PMID 30428063, 2019). "Melanomas which are wild type for BRAF, NRAS, and NF1 show amplifications of KIT, platelet-derived growth factor receptor α (PDGFRA), and vascular endothelial growth factor receptor 2 (VEGFR2) in 10–20% of cases." (PMID 30987166, 2019). "The authors also showed that activated BRAF/ERK pathway promotes glycolytic phenotype in melanoma cells by downregulating the expression of the mitochondrial biogenesis and function factor, PGC-1α, thereby inhibiting the mitochondrial oxidation." (PMID 30487597, 2019). "Strikingly, hemizygous deletion of Atg5 enhances melanoma growth (compared to Atg5+/+ or Atg5−/−), metastatic power and resistance to targeted therapy, such as BRAF inhibitor." (PMID 31998652, 2019). "Melanomas characterized by the invasive transcriptional program, associated with high expression of AXL, show intrinsic resistance to BRAF and ERK inhibitors." (PMID 30710146, 2019). "Dual MAPK pathway inhibition (dabrafenib and trametinib) was proven to have strong anti-tumor activity and good safety profile in patients with BRAF-mutant melanoma brain metastases, BRAF-mutant NSCLC, and KRAS-mutant-positive NSCLC." (PMID 31652660, 2019). "In order to better evaluate the accuracy of the model, we checked the effect of BRAF and NRAS mutation or wild-type on the prognostic ability of melanoma in the same cohort." (PMID 31649871, 2019). "The chemotherapy of melanoma depends on four genetic types: including mutant BRAF, mutant RAS (N/H/K), mutant NF1, and Triple wild-type." (PMID 31380151, 2019). "To test the relevance of anti-apoptotic adaptation in vivo, we obtained RNA from three melanoma patients with BRAF-mutant melanomas before, and 14 days after starting single agent vemurafenib." (PMID 31727958, 2019).
melanoma (continued). "Upon development of resistance to BRAF-inhibitors, human melanoma cell lines further increase their production of CCL2." (PMID 31762942, 2019). "In our real‐world retrospective analysis, patients with advanced BRAF mutant melanoma treated with front‐line niv/ipi or aPD‐1 had longer survival compared to those treated with front‐line BRAF/MEKi." (PMID 31677253, 2019). "The ATP-competitive RAF inhibitors vemurafenib and dabrafenib show remarkable clinical activities in patients with BRAF(V600E/K) melanoma and received US Food and Drug Administration (FDA) approval for the treatment of this disease." (PMID 30679688, 2019). "Early studies of BRAF- and MEK-inhibitors targeting this pathway established that they were particularly active in BRAF mutant melanoma." (PMID 30905967, 2019). "At present, two BRAF-inhibitors, vemurafenib and dabrafenib, are approved for the treatment of advanced malignant melanoma." (PMID 31803366, 2019). "In the case of BRAF-mutant melanomas, tolerance to BRAF and MEK kinase inhibitors is associated with distinct phenotype plasticity of melanoma differentiation state and global alterations in gene expression programs." (PMID 31581557, 2019). "FDA-approved kinase inhibitors are now used for melanoma, including combinations of the MEK inhibitor trametinib, and BRAF inhibitor dabrafenib for BRAFV600 mutations." (PMID 31379943, 2019). "Meanwhile, proliferation and CD69 expression of NK cells are increased in the context of IL-2, which is important for NK cells to reinforce the antitumor activity of BRAF inhibitor by perforin-dependent pathway in a BRAF-mutant melanoma mouse model." (PMID 31134073, 2019). "The predictor set consists of dose-time expression for 21 proteins and the response set contains the mean apoptosis fractions observed in 10 BRAF V600E/D melanoma cell lines over multiple doses and time points." (PMID 31216980, 2019). "For our prospective experimental validation, we focused on drug combinations involving BRAF inhibitors for BRAF-mutant melanoma, as this represents the standard of care for these melanoma patients." (PMID 30820351, 2019). "Of the known melanoma driver mutations (BRAF, NRAS and NF1), only BRAF was mutated significantly more frequently in the better than in the poorer prognostic group (162/301 vs. 16/55; Fisher’s exact test, P = 0.001)." (PMID 31322504, 2019). "In particular, co-cultures of melanoma cells with fibroblasts lead to the protection of cancer cells from BRAF inhibitor (BRAFi) such as vemurafenib." (PMID 31739477, 2019). "Gains of 1q, 3p, and 17q occur more frequently in NRAS-mutant than in BRAF-mutant conjunctival melanomas." (PMID 31683701, 2019). "Our findings suggest that in visceral metastases of malignant melanoma BRAF- or NRAS-MAFs are rather heterogeneous and cannot be predicted from data of the primary tumor." (PMID 31391014, 2019). "Recently, it has been shown that, in melanoma cells, chodroitin-4-sulfate confers resistance to BRAF inhibitors by a mechanism involving an increased CK2/PTEN binding, with consequent PTEN inhibition." (PMID 31277672, 2019). "In these studies, melanoma patients bearing mutant-V600E BRAF had partial or complete response rates to vemurafenib between 48 and 81% with the median PFS extending beyond 7 months." (PMID 30975211, 2019). "Taken together, these reports suggest the mechanisms of BRAF inhibitor resistance and possible ways to improve the treatment of BRAF inhibitor-resistant advanced melanoma." (PMID 31514399, 2019). "Two human melanoma cell lines, derived from a primary amelanotic tumor —A375, and from metastasis to lymph nodes —WM9, were positively verified for the presence of BRAF V600E mutation." (PMID 31877948, 2019). "Treatment for BRAF-mutant melanoma was the first to improve by targeted therapy using BRAF and MEK inhibitors." (PMID 31379943, 2019).